HIF1A (hypoxia inducible factor 1 subunit alpha)
Diseases named in the same sentence as HIF1A in open-access papers (continued):
Sharing a sentence is not in itself a finding about the gene and the disease.
cyst (continued). "Therefore, MIF could qualify as a druggable target downstream of HIF-1α and cAMP in order to reduce cyst enlargement and preserve renal function." (PMID 32885302, 2020). "In this latter model, combined inactivation of Arnt, but not Hif-1α, ameliorated Vhl-associated renal cystic disease, implying that Hif-2α might be responsible for the cyst development associated with Vhl loss." (PMID 22014577, 2011). "HIF-1α and cAMP can induce the expression of MIF by primary tubular cells and cyst-lining epithelial cells and promotes cyst cell proliferation independently of macrophages." (PMID 35563296, 2022). "Next to HIF-1α and hypoxia, we found MIF being additionally regulated by cAMP which is a strong promotor of cyst growth." (PMID 32885302, 2020). "In conclusion, HIF-1α and cAMP regulate MIF in primary tubular cells and cyst-lining epithelial cells, and MIF promotes cyst growth in the absence of macrophages." (PMID 32885302, 2020). "However, cyst formation in PKD leads to localized areas of hypoxia, as evidenced by increased HIF-1α in PKD kidneys, which is the substrate of CMA, and HIF-1α degradation via CMA is known as a major regulator of HIF-1 activity." (PMID 35159216, 2022). "In ADPKD, HIF-1α does not affect early cyst formation but rather, it is important for cyst growth and enlargement in later stages of the disease." (PMID 33920158, 2021). "We therefore conclude that inactivation of Hif-1α or Hif-2α, either alone, or in combination, is not sufficient to initiate cyst formation or to disrupt the renal tubule architecture." (PMID 22014577, 2011). "Surprisingly we found that, rather than ameliorating cyst development, combined inactivation of Hif-1α (but not Hif-2α) and Fh1, greatly exacerbated cystic hyperplasia." (PMID 22014577, 2011). "In PKD, HIF-1α may not disturb initial cyst formation, but it is important for cyst progression and expansion in later stages of the disease." (PMID 38397444, 2024). "Interestingly, HIF-1α and cAMP showed synergistic upregulation of MIF in cyst-forming cells." (PMID 32885302, 2020). "We speculate that in the absence of HIF-1α inhibition, the cyst wall of ACP rapidly expands and the cyst fluid fills quickly, resulting in the gradual increase of space occupancy, blocking the circulation of cerebrospinal fluid, and causing ventricular dilatation over time and hydrocephalus." (PMID 36091021, 2022). "Furthermore, cyst formation was not inhibited in double Fh1/Hif-1α KO mice, and these cysts also grew larger, suggesting that HIF1A may indeed be a tumour suppressor in this context." (PMID 30767037, 2019). "Double-knockout mouse models for both VHL/HIF-1α and VHL/HIF-2α however do not develop kidney cysts, indicating the importance of both proteins for cyst formation." (PMID 28934953, 2017).
metabolic syndrome (27 papers, 2010 to 2026). A cluster of metabolic risk factors for CARDIOVASCULAR DISEASES and TYPE 2 DIABETES MELLITUS. "The altered expression of hsa-miR-199a-3p influences energy homeostasis and metabolic adaptation via the suppression of IGF1R (insulin-like growth factor 1 receptor) and HIF1A (hypoxia-inducible factor 1-alpha), which are associated with metabolic syndrome." (PMID 40699679, 2025). "More recently, the importance of functional crosstalk between WWOX and HIF1α has also been reported in mice with Wwox-specific ablation in skeletal muscle, that is an animal model associated to the phenotype resembling metabolic syndrome." (PMID 33520443, 2021). "We next measured triglyceride (TG) levels to examine dyslipidemia and found that myeloid-specific Hif-1α KO mice exhibited significantly decreased TG levels in both eWAT and plasma than WT mice." (PMID 39473019, 2024). "This is complemented by our previously cell experiment which proved DLT had positive effects in improving dyslipidemia and arteriosclerosis by inhibiting Angptl4 protein levels through HIF-1α-Angptl4 mRNA signaling pathway." (PMID 36285165, 2022). "Consistently with this prior work, we found that HIF-1α was overexpressed in metabolic syndrome rats, compared to control rats, and that osthole administration could partially prevent these findings." (PMID 37237888, 2023). "We observed a significant increase in the expression of hif-1α on CD8+Tc amongst COVID(+) patients with metabolic syndrome, accompanied by a mild increase in glut-1 expression, suggesting that patients with prior metabolic comorbidities may have an increased hypoxia-driven anaerobic glycolysis." (PMID 37029220, 2023). "MUO patients exhibited higher HIF1A expression (p = 0.03) and strong correlations between CCL2 and dyslipidemia (total cholesterol, triglycerides)/dysglycemia (fasting glucose) (r = 0.45, p = 0.03; r = 0.52, p = 0.01; r = 0.63, p = 0.001, respectively)." (PMID 40943138, 2025). "The results indicated that quercetin had an excellent binding activity with many targets, including CCND1, HIF1A, MYC, AKT1, and EGFR; therefore, it might be a key compound for the effect against dyslipidemia." (PMID 35722157, 2022).
small cell lung carcinoma (27 papers, 2009 to 2026). Small cell lung cancer (SCLC) is a highly aggressive malignant neoplasm, accounting for 10-15% of lung cancer cases, characterized byrapid growth, and early metastasis. "HIF‐1α specifically modifies the expression of related tumor genes after translation to adapt to the hypoxic environment, like breast, colon, and small cell lung cancers, and HIF‐1α expression increases." (PMID 41427004, 2025). "Topotecan, which is approved for cervical, ovarian, and small-cell lung cancers, acts as both a DNA topoisomerase I inhibitor and a HIF1α inhibitor." (PMID 38893207, 2024). "Consistently, our results of KEGG analysis also showed that the circRNA-related target genes, such as HIF1A and NFKBIA, were mainly associated with two signaling pathways: HIF-1 signaling pathway and small cell lung cancer." (PMID 37674577, 2023). "The effect of HIF-1α on the angiogenic potential of small cell lung cancer (SCLC) significantly upregulated the expression of pro-angiogenic genes including VEGF-A, TNFA1P6, PDGFC, FN1, MMP 28 and MMP14." (PMID 31835751, 2019). "HIF-1α is highly expressed in small-cell lung cancer and aids in predicting the overall survival of patients, as well as in selecting patients most likely to benefit from HIF-1α-targeted therapies." (PMID 24765145, 2014). "Treatment of small cell lung cancer cell line with imatinib, a specific inhibitor of the protein tyrosine kinases c-kit, and platelet-derived growth factor receptor resulted in inhibition of c-kit-induced HIF-1α and VEGF expression." (PMID 23671874, 2013). "Hypoxia-inducible factor-1 alpha (HIF-1α) maybe an important regulatory factor for angiogenesis of small cell lung cancer (SCLC)." (PMID 21843314, 2011). "Wan and Wu explored the effects of HT on HIF-1α expression, proliferation, and lung cancer angiogenesis using NSCLC and small cell lung cancer (SCLC) cell lines." (PMID 35453310, 2022). "We also knocked down the expression of HIF-1α in hepatocyte cell line MIHA and non-small cell lung cancer cell line A549." (PMID 33046996, 2020). "We previously demonstrated that small cell lung carcinoma (SCLC) cells lack HIF-2α protein expression, whereas HIF-1α in these cells is expressed at both acute and prolonged hypoxia." (PMID 28430666, 2017). "The lack of HIF-1α may be compensated by MYC/MYCL-mediated glutaminolysis, which circumvents HIF-1α-dependent glycolysis in human small cell lung carcinoma cell lines during hypoxia." (PMID 31036602, 2019).
keloid (26 papers, 2008 to 2025). An irregularly shaped, elevated mark on the skin caused by deposits of excessive amounts of collagen during wound healing. "In this study, we first identified a crucial role for HOXC6 in the pathogenic mechanism of KFs in keloids and documented that HIF-1α positively regulates HOXC6 expression in KFs, thereby contributing to the progression of keloids." (PMID 35547861, 2022). "Given the lack of previous reports of the role of HOXC6 in keloid, we further validated the significance of high HOXC6 expression in keloid tissue samples and KFs and explored the potential pathogenic mechanism of HIF-1α-induced HOXC6 expression in KFs." (PMID 35547861, 2022). "Shortage of HIF-1α can be caused to form an intractable ulcer, whereas HIF-1α overexpression in dermal fibroblasts, in turn, can be led to fibrotic disease such as keloid formation." (PMID 34407893, 2021). "It is recognized that the hypoxic microenvironment exists inside of keloids and causes the accumulation of HIF-1α." (PMID 25777304, 2015). "A previous study demonstrated that a high HIF-1α expression in keloids was closely associated with the tumor bioenergetic characteristics and tumor metastasis." (PMID 25777304, 2015). "Immunohistochemical analysis of keloid tissues indicated that vimentin-expressing fibroblasts in the central zone undergo autophagy and glycolysis at higher levels than those in the marginal zone, which was associated with the expression level of HIF-1α." (PMID 38279232, 2024). "Due to the association between HIF-1α and EMT markers in keloid scar specimens and hypoxia-induced phenotypic changes in keratinocytes, HIF-1α may potentially provoke or intensify EMT markers during human keloid scar formation." (PMID 25777304, 2015). "By suppressing the PI3K/Akt/HIF-1α axis, quercetin sensitizes keloid fibroblasts to ionizing radiation, improving therapeutic efficacy (Si L-B." (PMID 41424791, 2025). "Quercetin enhances the radiosensitivity of keloid fibroblasts by promoting apoptosis through PI3K/Akt-dependent inhibition of HIF-1α." (PMID 41424791, 2025). "Hypoxia and HIF-1α promote keloid development through the activation of the TGF-β/SMAD and the toll-like receptor (TLR) 4/NF-κB pathways and increasing collagen production." (PMID 38279232, 2024). "This signaling, along with HIF-1α, contributes to collagen deposition under hypoxic conditions, which is an essential factor in the formation of keloids." (PMID 37953287, 2023). "Numerous studies have suggested a significantly higher HIF-1α level in keloids than in normal skin tissues." (PMID 35547861, 2022). "HIF-1α was also shown to participate in the development of keloids by activating the TGF-β and NF-κB pathways." (PMID 35547861, 2022). "There are significant differences in the expression of VEGF, CD31, and HIF-1α in radiated skin and its surrounding normal skin in recurred keloid patients." (PMID 36316928, 2022). "As a core marker of hypoxia, hypoxia-inducible factor-1α (HIF-1α) was also observed to be expressed at high levels in keloids compared to normal skin." (PMID 35547861, 2022). "Second, we did not conduct bioinformatics analysis to identify the mechanic role of VEGF, CD31, and HIF-1α in keloid development and recurrences." (PMID 36316928, 2022). "In keloid tissue, the elevated necroptosis marker was confirmed, and with the HIF-1α inhibitor, the defective autophagy, necroptosis and fibrosis was decreased in KF." (PMID 35757697, 2022). "Second, keloids are characterized by hypoxia and stimulating keloid-derived keratinocytes with hypoxia-inducible factor (HIF)-1α in vitro induces them to develop a fibroblast-like appearance and enhanced invasiveness." (PMID 35743263, 2022). "There are significant differences in the expression of VEGF, CD31, and HIF-1α in the recurred keloid skin after radiotherapy and normal skin." (PMID 36316928, 2022).
keloid (continued). "Overall, our results indicate the importance of the HIF-1α/HOXC6/ERK pathway in keloid growth and invasion, and further molecular mechanistic research and in vivo experiments are warranted to validate the clinical utility of these findings." (PMID 35547861, 2022). "The expression of VEGF, CD31, and hypoxia inducible factor-1α (HIF-1α) protein in the keloid-recurred skin (RN) group was higher than the normal skin group via immunohistochemistry (IHC) and Western blotting analysis." (PMID 36316928, 2022). "Our work expands on the current literature to directly link JAK1/2, STAT3, and HIF1α to keloid pathology, folic acid responses, and Warburg physiology; however, other signaling pathways beyond these identified pathways are likely involved for each finding." (PMID 33662027, 2021). "Hif1α is responsible for upregulating Glut1 and glucose uptake, as well as various glycolytic enzymes, and is activated in hypoxic conditions such as keloids." (PMID 32750036, 2020). "Previous studies report that ECM accumulation in keloid tissue results from constant hypoxia and that HIF-1α is highly expressed in keloid tissue." (PMID 31137604, 2019). "Immunohistochemistry staining showed higher protein levels of HIF-1α and Smad2/3 in keloid dermis than those in normal dermis." (PMID 29423039, 2018). "Hypoxia up-regulated TGF-β1, Smad2/3, p-Smad2/3, Smad4, and total collagen in both normal and keloid fibroblasts via HIF-1α, which was attenuated by HIF-1α inhibition, but TβRII levels were not significantly altered." (PMID 29423039, 2018). "In this study, we detected the expression of HIF-1α, as well as that of epithelial and mesenchymal markers in keloid tissue biopsy speciments." (PMID 25777304, 2015). "Due to exposure to constant hypoxic conditions, hypoxia-inducible factor-1α (HIF-1α) is highly expressed in keloid tissue and is an important transcriptional regulator which helps cells adapt to the hypoxic microenvironment." (PMID 25777304, 2015). "This indicates that HIF-1α is involved in the initiation and modulation of the expression of epithelial and mesenchymal markers in keloid keratinocytes." (PMID 25777304, 2015). "On the contrary, the marked restoration in the expression of E-cadherin and ZO-1 suggested the distinctive importance of HIF-1α signaling in EMT in keloid keratinocytes (P<0.05 and 0.05, respectively)." (PMID 25777304, 2015). "In conclusion, the present findings demonstrate that the hypoxia/HIF-1α microenvironment provides a favorable environment for keloid-derived keratinocytes to adopt a fibroblast-like appearance through EMT." (PMID 25777304, 2015). "It was observed that HIF-1α was highly expressed in the epithelial layer of the keloid skin specimens, particularly along the basal layer, which was adjacent to the dermis." (PMID 25777304, 2015). "Moreover, PI3K/AKT sustains redox homeostasis and forms a positive feedback loop with HIF-1α, further amplifying glycolytic reprogramming and reinforcing the tumor-like behavior of keloids." (PMID 41424791, 2025). "Thus, research on the role of HIF-1α in keloid pathogenesis would provide a new opportunity to develop therapeutic approaches." (PMID 38279232, 2024). "HIF-1α and TGF-β/Smad signaling pathway are closely linked with the formation of keloid." (PMID 37910782, 2023). "Further experiments are needed to specify the molecular mechanisms underlying the interaction between HIF-1α and HOXC6, which might provide great insights into the pathogenic mechanism of hypoxia in keloids." (PMID 35547861, 2022). "However, the specific mechanism by which HIF-1α affects the progression of keloids is far from clear." (PMID 35547861, 2022). "HIF-1α is upregulated in keloid fibroblasts, and HIF-1α inhibition reduces collagen levels in keloid as well as hypertrophic scar fibroblasts introducing a pathophysiological link between a hypoxic microenvironment and collagen production in keloids and hypertrophic scars." (PMID 33202590, 2020).
keloid (continued). "Because hypoxia/HIF-1α may be a key environmental factor in the EMT process affecting keloid, HBOT might potentially reverse the hypoxic condition and thus also make it possible to ameliorate the EMT phenomenon." (PMID 30024539, 2018). "Our study demonstrated that keloid keratinocytes underwent a transition from an epithelial to a mesenchymal phenotype in response to HIF-1α, with a marked upregulation in the expression of vimentin and fibronectin, and a decrease in E-cadherin and ZO-1 expression." (PMID 25777304, 2015). "In the current study, we hypothesized that hypoxia/HIF-1α is a key factor in the transition of keloid keratinocytes into mesenchymal-type cells." (PMID 25777304, 2015). "By acquiring a fibroblast-like appearance, the keloids secrete more ECM, and this causes further HIF-1α accumulation, which may exacerbate the keloid malignant growth pattern." (PMID 25777304, 2015). "Moreover, HIF-1α triggers both the TGF-β/Smad and TLR4/MyD88/NF-κB signaling pathways, and the synergy between these pathways could facilitate keloid formation, and selective HIF-1α inhibitors consistently lead to a reduction in collagen levels." (PMID 39114830, 2024). "This means that HIF-1α may also be a potential indicator for the treatment of keloids." (PMID 36316928, 2022). "Additionally, Hif1α protein expression in keloids was increased (1.00 vs. 0.28, P < 0.001)." (PMID 32750036, 2020). "In keloid tissue, the elevated level of HIF-1α protein caused by more serious hypoxia conditions may activate the TGF-β1/Smad pathway, whereupon both HIF-1α and the TGF-β1/Smad pathway act to promote collagen deposition during keloid formation." (PMID 29423039, 2018). "As a result, hypoxia/HIF-1α may enhance the invasive capacity of keloid keratinocytes." (PMID 25777304, 2015). "Thus, the pathway (MMP2 up-regulated by HIF1A) may be involved in the expansion of keloids and merit further experimental study." (PMID 18620599, 2008). "IL-17 induces autophagy dysfunction to promote inflammatory cell death and fibrosis in keloid fibroblasts via the STAT3 and Hypoxia Inducible Factor-1α (HIF-1α) dependent signaling pathways." (PMID 39799030, 2025). "HIF-1α and high temperature requirement factor A1 activate the TGF-β1/Smad pathway and promote keloid formation." (PMID 37033989, 2023). "Through upregulation of hypoxia-inducible factor-1α (HIF-1α) and STAT3, IL-17 impairs autophagy of both normal and keloid fibroblasts, resulting in increased necroptosis and fibrosis." (PMID 37033989, 2023). "The expression of HIF-1α and STAT3 was significantly increased in the transitional region where skin tissue changes into keloid tissue." (PMID 35757697, 2022). "However, the specific mechanism by which HIF-1α promotes keloid development remains unclear." (PMID 35547861, 2022). "The HIF-1α/HOXC6/ERK axis promotes proliferation, migration and ECM production by KFs, contributing to the progression of keloids." (PMID 35547861, 2022). "The expression of IL-17, HIF-1α and STAT3 was significantly increased in keloid tissue, and autophagosome-to autophagolysosome conversion was defective in KF." (PMID 35757697, 2022). "HBOT significantly decreased the expression levels of vimentin, fibronectin, and HIF-1α, suggesting that HBOT has protective effects against the EMT phenomenon during keloid development." (PMID 30024539, 2018). "In this study, keloid tissue after HBOT demonstrated lower expression levels of vimentin, fibronectin, VEGF, and HIF-1α." (PMID 30024539, 2018). "In order to confirm the mechanisms through which HIF-1α participates in hypoxia-mediated EMT in keloid-derived keratinocytes, the HIF-1α gene was knocked down by siRNA in keloid-derived keratinocytes." (PMID 25777304, 2015). "In addition, collagen production and the epithelial-to-mesenchymal transition in keloid are regulated by HIF-1α, and blockade of HIF-1α suppresses the fibrotic reaction in keloid tissue." (PMID 35757697, 2022).